ADD3 (adducin 3)
Diseases named in the same sentence as ADD3 in open-access papers (continued):
Sharing a sentence is not in itself a finding about the gene and the disease.
Ewing sarcoma (2 papers, 2021 to 2024). A small round cell tumor that lacks morphologic, immunohistochemical, and electron microscopic evidence of neuroectodermal differentiation. "This interaction inhibits the inclusion of ADD3 exon 14, promoting the mesenchymal phenotype of Ewing's sarcoma cells." (PMID 39243148, 2024). "In particular, EWS-FLI1 reduces RBFOX2 binding to the ADD3 pre-mRNA, thus increasing its long isoform, which represses the mesenchymal phenotype of Ewing sarcoma cells." (PMID 34009296, 2021). "Altogether, these data strongly suggest that the regulation of ADD3 splicing by EWS-FLI1 is important for Ewing sarcoma biology." (PMID 34009296, 2021). "By RT-PCR, we verified that EWS-FLI1 promotes the ADD3-L isoform, which contains exon 14, whereas RBFOX2 reduces the inclusion of exon 14 of ADD3 in Ewing sarcoma cells." (PMID 34009296, 2021). "RNA-seq analysis of a collection of 43 Ewing tumors showed that the relative inclusion levels of ADD3 exon 14 were positively correlated with EWS-FLI1 expression levels (P = 0.017; R = 0.39)." (PMID 34009296, 2021). "We further validated the regulation of ADD3 exon 14 splicing by EWS-FLI1 depletion using siRNA transfection in a second Ewing sarcoma cell line (MHH-ES1)." (PMID 34009296, 2021). "Moreover, in the Ewing's sarcoma cell line (A673), RBFOX2 has been found to bind to ADD3 (a phenotypic driver of Ewing's sarcoma) pre‐mRNA." (PMID 39243148, 2024). "Regarding this hypothesis, we show that the EWS-FLI1-induced exon 14-containing isoform of ADD3, ADD3-L contributes to the repression of the mesenchymal phenotype in Ewing sarcoma cells." (PMID 34009296, 2021). "The observation that RBFOX2 binding to its target pre-mRNA, ADD3 is increased after depletion of EWS-FLI1 in Ewing sarcoma cells, suggests that EWS-FLI1 expression may interfere with RNA binding by RBFOX2." (PMID 34009296, 2021).
heart failure (2 papers, 2024 to 2025). Inability of the heart to pump blood at an adequate rate to meet tissue metabolic requirements. "MR analysis identified significant causal associations between the genes implicated in BW loss (ADD3, HSPA12A, SLC18A2, PDZD8, DUSP5, CASP7) as well as EF% and LV volumes (GPC6, UGGT2, SLAIN1, POU4F1, MBNL2) in BXD mice post-DOX and heart failure (HF) outcomes in humans." (PMID 40321772, 2025).
malignant glioma (2 papers, 2020 to 2021). A grade III or grade IV glioma arising from the central nervous system. "By correlating patient characteristics to the occurrence of allelic loss, we determined whether the aberrant expression of ADD3 in malignant glioma results from LOH10q, which may be involved in tumor relapse and malignant progression." (PMID 34970477, 2021). "All of these could be the potential mechanisms and the pathophysiological consequences that underlie allelic loss of ADD3 in malignant gliomas, particularly during disease progression." (PMID 34970477, 2021).
Obesity (2 papers, 2021 to 2024). Accumulation of substantial excess body fat. "Importantly, we have identified, for the first time, an association between the adducin (ADD3 rs3731566) SNP and the rs518054 SNP in the 9p21–23 region with obesity." (PMID 39464190, 2024).
acute lymphoblastic leukemia (1 paper, 2010). Leukemia with an acute onset, characterized by the presence of lymphoblasts in the bone marrow and the peripheral blood. "Interestingly, ADD3 was also detected in acute lymphoblastic leukemia as a fusion protein with NUP98." (PMID 21118496, 2010).
bipolar disorder (1 paper, 2022). A disorder of the brain that causes unusual shifts in mood, energy, activity levels and the ability to carry out day-to-day tasks. "Another gene ADD3 was discovered by the Psychiatric Genomics Consortium Bipolar Disorder Working Group with a large-scale meta-analysis." (PMID 36238831, 2022).
bladder cancer (1 paper, 2014). "Our result showed the same AS event difference between in the UCB and non-tumor tissue, suggesting that the long isoform of ADD3 might be also a cancer-specific transcript in bladder cancer." (PMID 24622401, 2014). "Some cancer-associated DSGs in our result were reported in the other cancers but not reported in the bladder cancer yet, such as PDGFA, MACF1, ADD3 and NUMB." (PMID 24622401, 2014).
cholestasis (1 paper, 2017). Impairment of the bile flow caused by obstruction within the liver, or outside the liver in the bile duct system. "As overexpression of ADD3 could facilitate deposition of actin, adhesion and accumulation of epithelial cells, it may result in a poor contraction and poor bile flow, exacerbating cholestasis." (PMID 28902846, 2017).
Cirrhosis (1 paper, 2023). A chronic disorder of the liver in which liver tissue becomes scarred and is partially replaced by regenerative nodules and fibrotic tissue resulting in loss of liver function. "Our results were obtained from this particular analysis in 20 BA patients with a small age range, we could not exclude the possibility that autoantibodies to ADD3 attributed to fibrosis and cirrhosis in the later stage of BA." (PMID 37834180, 2023).
colorectal polyps (1 paper, 2017). "In contrast, reduced expression of ADD3 and its splicing isoforms have been observed in colorectal polyps, suggesting that changes in ADD3 and its isoforms expression in polyps are the early stage of CRC, leading to the report of the change of ADD3-Ia/ADD3-Ib ratio useless." (PMID 28476036, 2017).
depressive disorder (1 paper, 2023). A melancholy feeling of sadness and despair. "Gene-trait association was mostly seen with SCZ, additionally, TRANK1, ADD3 and CDAN1 were TWAS positive for BD, OSBPL3 for depressive disorder and CACNA1G for ADHD." (PMID 38104115, 2023).
hepatoblastoma (1 paper, 2021). Hepatoblastoma (HB) is a malignant hepatic tumor and is the most common pediatric liver cancer. "GATA4 is also highly expressed in most hepatoblastomas and correlates with a mesenchymal, migratory phenotype in hepatoblastoma cells by regulating the expression of ADD3, AHNAK, and IGFBP1." (PMID 33648545, 2021).
myopia (1 paper, 2016). "Among the mRNAs targeted by differentially expressed miRNAs, there were several (Prkar1a, Rims2, Map2, Gabarapl1, Htr7, Add3, Erc1, Nlgn1) which were involved in synapse formation and function suggesting that synaptic function was one of the biological processes affected in form-deprivation myopia." (PMID 27622715, 2016).
oral cancer (1 paper, 2024). "However, differential expression was observed with TRIM2, ADD3, and ABCE1 among some of the oral cancer cell lines." (PMID 38396844, 2024).
tumor (14 papers, 2010 to 2025). "For example, only variants in ADD3 have been associated with hereditary cerebral palsy, and in the context of GBM, only ADD3 has been implicated in tumor progression and resistance to therapy." (PMID 39592188, 2025). "While it primarily functions as a cytoskeleton protein, ADD3 is characterized as a negative regulator of tumor growth and is negatively associated with malignant phenotypes such as angiogenesis in GBM." (PMID 34970477, 2021). "Data further suggest the role of ADD3 as a novel tumor suppressor, whereby the loss of ADD3 is indicative of a progressive disease that may at least partially account for rapid disease progression in GBM." (PMID 34970477, 2021). "Suggested as a tumor suppressor and survival predictor on chromosome 10q, ADD3 was valuable for prognostic assessments in LGG." (PMID 38338932, 2024). "Of the five allelic loci examined, only LOH of D10S173 at the ADD3/MXI1 locus was a predictor of shorter survival and had a significant association with tumor grade and proliferative index." (PMID 34970477, 2021). "ADD3 was found to be significantly downregulated in GBM, and such loss was associated with enhanced tumor growth." (PMID 34970477, 2021). "We found that allelic loss in both D10S173 (ADD3/MXI1 locus) and D10S1137 (MGMT locus) were positively associated with tumor grading and proliferative index (MIB-1)." (PMID 34970477, 2021). "ADD3 is located on chromosome 10q25.1-25.2, which is known to be a functional tumor suppressor region." (PMID 34970477, 2021). "It acts a tumor-suppressive role by targeting genes sex-determining region Y-box 9 and adducin 3, thus mediating invasion and malignant characteristics." (PMID 26320189, 2015). "Cassette exon inclusion in the mouse ortholog of ADD3 is high only in tumours originating from cell lines with a high potential for metastasis." (PMID 21118496, 2010). "We reported previously on the putative tumor-suppressive function of ADD3 in GBM." (PMID 34970477, 2021). "ADD3 is a putative tumor suppressor that may also serve as a promising marker on 10q in predicting survival." (PMID 34970477, 2021). "Alteration of ADD3 may also modulate the tumor microenvironment mediated by changes in focal adhesion as well as cell–cell contacts." (PMID 34970477, 2021). "Our findings further suggested that ADD3 is a putative tumor suppressor in GBM." (PMID 34970477, 2021). "TMX4, ALPL, PTX3, BHLHE40, TNFRSF12A and CST3 demonstrated significant overexpression in LUSC tumour tissues, whereas CLDN1, VKORC1 and ADD3 exhibited significant underexpression in the HPA database." (PMID 38520221, 2024). "Notably, TMX4, ALPL, PTX3, BHLHE40, TNFRSF12A and CST3 demonstrated significant overexpression in LUSC tumour tissues, whereas CLDN1, VKORC1 and ADD3 exhibited significant underexpression." (PMID 38520221, 2024). "We confirmed an aberrant increase of cassette exon skipping in tumor specimens for PACSIN2 exon 8, DIAPH1 exon 2, FGFR1OP2 exon 4, MARK3 exon 16, DST exon 93, LMO7 exon 10, and RBM5 exon 7, whereas ADD3 exon 13, MAP3K7 exon 12, and MARK2 exon 15 were preferentially included in tumor specimens." (PMID 34202984, 2021). "qRT-PCR results confirmed that the overall amount of ADD3 did not change between tumour and NAT; thus, FC and SI values were similar." (PMID 21118496, 2010). "Results showed that the exon skipping events of FIP1L1, NKTR, and ADD3, but not ATP5F1C, occurred in most tumor tissues highly expressing CDYL2a compared to matched normal breast tissues." (PMID 32373210, 2020). "However, we focused our attention on PACSIN2, DIAPH1, MARK3, ADD3, MAP3K7, and MARK2 cassette exons as these events were validated in both normal and cancer cell lines and in non-pathological and tumor breast specimens." (PMID 34202984, 2021).
cancer (12 papers, 2010 to 2025). A tumor composed of atypical neoplastic, often pleomorphic cells that invade other tissues. "We link this to the notion that Onda-11 cells were shown to be strongly dependent on ADD3 in the Cancer DepMap project, whereas U-87MG were not." (PMID 39592188, 2025). "Specifically, genes like ADD3 and LYZ have been previously implicated in potential roles related to the progression and metastasis of certain cancers." (PMID 38240686, 2024). "Adducin 3 (ADD3) is a key assembly factor of the actin cytoskeleton found to be abnormally expressed in various cancers." (PMID 37952042, 2023). "Most of the candidate genes of which we confirmed cancer-specific AS in NSCLC are also involved in these processes (ADD3, CLSTN1, FN1, MYO18A, NUMB, SYNE2, and TPM1)." (PMID 21118496, 2010). "Compared with MXI1, less is known about the role of ADD3 in cancer." (PMID 34970477, 2021). "It was concluded that alternative splicing events of ADD3 and cassette exon inclusion may potentially play a role in cancer progression." (PMID 29862265, 2018). "Therefore, further studies on ADD3 should be done to understand the relationship of its alternative splicing with cancer." (PMID 22905095, 2012). "Six genes, including ADD3, CTNND1, EPB41L3, F3, MUC4 and PDGFA, showed cancer-tissue-specific DES events." (PMID 22905095, 2012). "In fact, we showed that ADD3, as an intrinsic factor promoting morphological heterogeneity, has a critical role in cancer cell survival both cell-autonomously and nonautonomously." (PMID 39592188, 2025). "However, the basis behind ADD3 downregulation has not been identified for which both genetic and epigenetic modifications should be taken into consideration when studying its functional characteristics in cancer cells." (PMID 34970477, 2021).
renal disease (5 papers, 2017 to 2025). "Of these genes, adducin 3 (Add3) appears to be a likely candidate for the altered K+ channel activity and the myogenic response, because Milan normotensive rats share the same variant in Add3 as FHH rats, and they also develop renal disease as they age." (PMID 27789734, 2017). "To address the phenotypic effects of the ADD3 and KAT2B knockdowns, we analyzed adhesion and migration, which are processes typically affected in kidney diseases such as SRNS." (PMID 29768408, 2018).
heart disease (1 paper, 2018). "Altogether, our studies describe the expansion of the phenotypic spectrum in ADD3 deficiency associated with a homozygous likely pathogenic KAT2B variant and thereby identify KAT2B as a susceptibility gene for kidney and heart disease in ADD3-associated disorders." (PMID 29768408, 2018).
ADD3 also shares sentences with these, for which no sentence is quoted: acute myocardial infarction (2 papers); cataract (2); microcephaly (2); adenocarcinoma (1); astrocytomas (1); Cerebral arteriopathy with subcortical infarcts and leukoencephalopathy 1 (1); diabetes (1); epilepsy (1); episodic ataxia type 6 (1); fibrosis (1); hepatocellular carcinoma (1); hypertensive renal disease (1); neurodevelopmental disorder (1); schizophrenia (1); spastic quadriplegic cerebral palsy (1); squamous cell carcinoma (1); Stroke (1).